RETN (resistin)
Diseases named in the same sentence as RETN in open-access papers (continued):
Sharing a sentence is not in itself a finding about the gene and the disease.
hypothyroidism (8 papers, 2013 to 2025). Abnormally low levels of thyroid hormone. "A prior animal study has demonstrated that hypothyroidism is associated with elevated resistin mRNA levels in WAT." (PMID 36686437, 2022). "The analysis of the anti-TPO antibody revealed the positive association between the anti-TPO value and the serum concentrations of visfatin and resistin in the T2DM patients with hypothyroidism." (PMID 36830883, 2023). "T2DM patients with clinical hyper- or hypothyroidism had higher levels of chemerin and resistin, compared with the T2DM patients with subclinical thyroid dysfunctions." (PMID 36830883, 2023). "They analysed leptin, adiponectin and resistin in children with untreated Graves’ disease and hypothyroidism in Hashimoto’s thyroiditis." (PMID 35399935, 2022). "However, the association between resistin levels and hypothyroidism remains unclear." (PMID 36686437, 2022). "There were no proportional correlations between resistin levels and severity of hypothyroidism, whereas the total HrT group showed positive correlation between resistin and TSH levels." (PMID 23533949, 2013). "In the T2DM patients coexisting with hypothyroidism, the serum chemerin- and resistin-concentrations had a positive correlation with FBG only, while in the T2DM patients with hyperthyroid dysfunction, chemerin and resistin showed positive association with FBG and HOMA-IR." (PMID 36830883, 2023). "There was no substantial difference in resistin levels between patients with hypothyroidism (MD = –0.31, 95% CI = –0.96–0.35, P > 0.05, I2 = 36%) and subclinical hypothyroidism (MD = 0.31, 95% CI = –0.33–0.96, P > 0.05, I2 = 0%) before and after treatment." (PMID 36686437, 2022). "Study from Bossowski only found a decrease of resum resistin in untreated GD patients compared with hypothyroidism, but they did not explore the change of resistin level after normalization of thyroid function." (PMID 27637079, 2016).
knee osteoarthritis (8 papers, 2016 to 2025). "Resistin was directly associated, and visfatin was inversely associated, with clinical severity in female patients with knee osteoarthritis with joint effusion." (PMID 27629533, 2016). "In patients with knee osteoarthritis, the serum levels of resistin were related to cartilage defects and bone marrow lesions." (PMID 36097281, 2022). "On the other hand, serum resistin increases in subjects with bilateral knee osteoarthritis, and in patients with hip and knee osteoarthritis." (PMID 34948944, 2021). "Kellgren-Lawrence grade, physical exercise, all anthropometric measurements (especially waist circumference), tumor necrosis factor α, and high levels of leptin, resistin, and ostepontin were related to knee osteoarthritis severity." (PMID 27629533, 2016). "Based on the results of an Italian study, mud bath therapy can decrease the serum level of adiponectin and resistin that may play a protective role in the course of knee osteoarthritis." (PMID 31377868, 2020). "In the present study, we sought to generate hypotheses regarding the associations of serum levels of interleukin (IL)-17, adiponectin, and resistin with magnetic resonance imaging-measured infrapatellar fat pad (IPFP) size and signal intensity alterations in patients with knee osteoarthritis (OA)." (PMID 27566142, 2016).
malnutrition (8 papers, 2012 to 2025). Inadequate nutrition resulting from poor diet, malabsorption, or abnormal nutrient distribution. "In the case of the nutrition status assessment using the MNA score (malnutrition, at risk of malnutrition, adequate nutritional status), the parameters for which statistically significant differences were determined include leptin and resistin." (PMID 36978817, 2023). "WAT contains large lipid droplets and releases adipokines (FFAs, TNF-α, IL-6, IL-10, resistin, leptin, and adiponectin) to maintain metabolic homeostasis and stores TG for future energy production during periods of malnutrition." (PMID 33947969, 2021). "For instance, in the study involving 80 senile patients, it was shown that the concentration of resistin increases with a decline in glomerular filtration rate (GFR), which may be related to malnutrition associated with the disease." (PMID 36978817, 2023). "Subsequently, we examined the impact of malnutrition on adipocytokines in T2DM by measuring the plasma levels of adiponectin, adipsin, resistin, leptin and visfatin in LBMI and NBMI individuals." (PMID 33183277, 2020).
preeclampsia (8 papers, 2019 to 2023). Preeclampsia is a hypertensive disorder of pregnancy that is characterized by new-onset hypertension with proteinuria presenting after 20 weeks of gestation, and depending on mild or severe forms may initially present with severe headache, visual disturbances, and hyperreflexia. "As others have found, we were not able to detect many other proinflammatory cytokines associated with preeclampsia, such as resistin or TNFα." (PMID 35329840, 2022). "As described in paragraph 6.3, several adipokines, such as adiponectin, leptin, resistin, visfatin and apelin, are also secreted by the placenta and have been implicated in metabolic adaptations to normal gestation, as well as in preeclampsia and other complications of pregnancy." (PMID 31505789, 2019). "As high resistin levels in the first trimester of pregnancy (up to 36.55 ng/mL) have been associated with an increased risk of developing preeclampsia, it has been proposed that resistin concentration could be added to the predictive and prognostic algorithms for this pathology." (PMID 35467263, 2022). "A recent study on pregnant women with type 1 diabetes mellitus has shown that, as early as the first trimester, the profiles of adipokine biomarkers related to insulin resistance (adiponectin, resistin, and others) increase the incidence of preeclampsia." (PMID 35329840, 2022). "Data concerning the changes in serum resistin levels in preeclampsia are both limited and conflicting." (PMID 33321877, 2020). "This study was aimed at determining the levels of serum adiponectin, leptin, resistin, visfatin and lipids during the first trimester in pregnant women and to evaluate the relationship between these biochemical markers and preeclampsia (PE)." (PMID 33014422, 2020). "As demonstrated in the cross-sectional study by Erol’s group, the resistin level for pre-eclamptic mothers was significantly higher (mild preeclampsia group: 3.3 ± 0.6 ng/mL, severe preeclampsia group: 3.8 ± 0.4 ng/mL) than for healthy mothers (2.6 ± 0.4 ng/mL)." (PMID 37764842, 2023). "Therefore, according to those results, increased serum resistin levels in women with preeclampsia might not be assumed to be related to placental production." (PMID 33321877, 2020).
gastric cancer (7 papers, 2014 to 2022). A primary or metastatic malignant neoplasm involving the stomach. "The promoter activity and transcription factor enzyme-linked immunosorbent assay revealed that resistin induced expression of SDF-1 mediated by NF-κB in gastric cancer cells." (PMID 24929539, 2014). "In this study, we evaluated the molecular mechanisms underlying the roles of resistin in controlling SDF-1 expression in gastric cancer cells." (PMID 24929539, 2014). "The essential role of resistin, as well as its association with gastric cancer, make it a factor of concern as well as a potential a biomarker for gastric cancer progression; therefore, it is clinically relevant to study the mechanism by which resistin influences tumor cells." (PMID 24929539, 2014). "An earlier study in gastric cancer identified induction of CXCL12-CXCR4 signaling by resistin, which can be another mechanism of angiogenesis-induction." (PMID 30131543, 2018). "Our findings provide evidence of the molecular mechanisms of SDF-1 expression and its secretion by resistin via a TLR4-dependent pathway in gastric cancer cells." (PMID 24929539, 2014). "Researchers have pointed out that resistin is the blood biological indicator of gastric cancer and is related to patient prognosis." (PMID 24929539, 2014). "This study demonstrated the mechanism by which resistin induces SDF-1 gene expression of gastric cancer cells." (PMID 24929539, 2014). "A limited number of studies have investigated the association of resistin and SDF-1 with gastric cancer." (PMID 24929539, 2014). "We found that treatment of gastric cancer cells with resistin resulted in the activation of signaling pathways mediated by TLR4." (PMID 24929539, 2014). "Human gastric cancer cell lines were exposed to doses of resistin; SDF-1 expression and secretion levels were then determined." (PMID 24929539, 2014). "Further studies are required to explore the potential role of the resistin/ TLR4 axis as an effective therapeutic agent against gastric cancer." (PMID 24929539, 2014). "Taken together, our data suggest the mechanism by which resistin induces SDF-1 expression in gastric cancer cells." (PMID 24929539, 2014). "Herein, we investigated the molecular mechanisms by which resistin influences the expression of SDF-1 in gastric carcinoma cells." (PMID 24929539, 2014). "Recent studies have demonstrated the essential role of the resistin cascade, and a higher expression of resistin was evident in intestinal-type gastric carcinomas with tumor differentiation, tumor invasion, and lymph node metastasis." (PMID 24929539, 2014). "To determine whether SDF-1 is induced by resistin, we exposed the human gastric cancer cell lines TSGH 9201 and AGS to a range of resistin doses and performed experimental assays." (PMID 24929539, 2014). "From this viewpoint, because chemokines have certain roles in microbial immune and inflammation responses, the resistin-induced secretion of SDF-1 may be correlated to the control of gastric cancer." (PMID 24929539, 2014). "We investigated the role of resistin signaling factors downstream of the p38 MARK and NF-κB activation sites that lead to SDF-1 transcriptional activation in TSGH 9201, and the pathophysiological implication of the role of resistin in gastric cancer should be further explored." (PMID 24929539, 2014). "Based on our results, it is possible that in gastric carcinoma cell, resistin induced pathway-related proteins may be studied as potential markers in terms of the prediction of response to treatment or prognosis." (PMID 24929539, 2014). "The ASCL2 shows a negative correlation with H. pylori-induced gastrointestinal inflammation, uses resistin as a regulator of inflammation, activates TLR signaling and TLR4 cascade, and positively correlates with gastric cancer by GSEA." (PMID 36008864, 2022).
gastric cancer (continued). "The level of resistin, which is a regulator of inflammation, activates TLR signaling and toll-like receptor 4 cascade in STAD and is positively correlated with gastric cancer." (PMID 36008864, 2022). "Thus far, no study has investigated the association of resistin and any known receptor to activate downstream MAPK kinase that further activate nuclear factor-κB (NF-κB p50/p65) in human gastric cancer." (PMID 24929539, 2014).
hepatocellular carcinoma (7 papers, 2014 to 2025). A malignant tumor that arises from hepatocytes. "Moreover, It has been mentioned that the release of various proteins from visceral adipose tissues, including adipokines, resistin, leptin, visfatin, and tumor necrosis factor α, can impact liver function, potentially causing inflammation, cirrhosis, and hepatocellular cancer." (PMID 38179344, 2023). "Recent study has shown that resistin inhibit the AMPK phosphorylation to modulate glucose metabolism in human hepatoma cells." (PMID 24555415, 2014). "Moreover, visceral adipose tissues secrete a variety of proteins such as adipokines, resistin, leptin, visfatin and tumour necrosis factor α which can influence the liver function and lead to inflammation, cirrhosis and hepatocellular cancer." (PMID 36039792, 2022). "Additionally, adipokines, resistin, leptin, visfatin, and tumor necrosis factor α (TNF-α) are proteins secreted by visceral adipose tissues that can affect how the liver functions and cause inflammation, cirrhosis, and hepatocellular cancer." (PMID 37374119, 2023). "Notably, resistin down-regulated PON1 expression occurred in hepatocellular carcinoma cultures." (PMID 31390816, 2019). "For example, in hepatocellular carcinoma (HCC), circulating levels of adiponectin, leptin, visfatin and resistin were significantly higher in HCC patients when compared with the control group." (PMID 40902078, 2025).
myeloma (7 papers, 2016 to 2025). "Regarding its role in multiple myeloma, one case-control study showed that serum resistin was lower in MM patients (n = 73, 9.4 ± 5.0 ng/mL) compared to gender and age-matched healthy controls (n = 73, 15.9 ± 6.8 ng/mL, p < 0.001)." (PMID 37637774, 2023). "BM adipocytes secrete several adipokines and growth factors (e.g., MCP-1, SDF-1α, leptin, TNFα, insulin, resistin) which recruit myeloma cells and promote myeloma growth and protection from chemotherapy." (PMID 34067236, 2021). "However, preclinical models have demonstrated that MM treatment results in significant decreases in Bcl-2 and Bcl-xL expression in myeloma cells, while the addition of resistin increases their expression." (PMID 41303900, 2025). "Therefore, further studies are needed to differentiate the effect of resistin secreted by the BMF from the effect of resistin secreted by other stromal cells on myeloma growth and survival." (PMID 30546345, 2018). "We next highlighted the ways in which BMAT may support MM, for example, through bioactive lipids (as a fuel source, signaling molecule, and a substrate for lipid peroxidation), and myeloma-supportive adipokines (e.g., IL-6, TNFα, MCP-1, PAI-1, IL-6, resistin, and leptin)." (PMID 27379019, 2016).
periodontal disease (7 papers, 2014 to 2025). "Moreover, another adipokine, resistin, has been implicated in the pathogenesis of periodontal disease." (PMID 41300847, 2025). "Periodontal diseases can affect overall health by altering the levels of adipokines (IL-1β, leptin, resistin, and adiponectin) in the serum, saliva, and GCF of obese female patients." (PMID 36767065, 2023). "Previous studies have shown that resistin levels increase with the severity of periodontal disease and decrease after periodontal therapy." (PMID 37798684, 2023). "Our previous research showed incremental elevation of resistin with periodontal disease activity and a reduced level of resistin, after periodontal therapy." (PMID 24692844, 2014).
pneumonia (7 papers, 2020 to 2024). An acute, acute and chronic, or chronic inflammation focally or diffusely affecting the lung parenchyma, caused by an infection in one or both of the lungs (by bacteria, viruses, fungi, or mycoplasma.). "Additionally, we found that the eQTL data supported the association between RETN RNA levels and a lower risk of pneumonia-related death, while the cis-eQTL, pQTL, and cis-pQTL data did not support this association." (PMID 37834432, 2023). "Showing marker potential, serum resistin levels were predictors of the prognosis of pneumonia severity and the need for invasive mechanical ventilation." (PMID 37238973, 2023). "In a group of 146 patients, which was stratified for pneumonia severity in mild, moderate, and severe illness, serum resistin levels were almost 2-fold higher in the latter group." (PMID 37238973, 2023). "Not only that, the symptoms of pneumonia were alleviated and the level of resistin was decreased in CAP patients after treatment." (PMID 34858392, 2021). "High serum resistin levels were also found in patients with pneumonia and chronic obstructive pulmonary disease." (PMID 33202617, 2020).
hyperandrogenism (6 papers, 2019 to 2025). Excessive secretion of androgens from the adrenal glands or gonads. "The expression of resistin is upregulated by androgens, therefore there is a positive association between hyperandrogenism and high levels of resistin in PCOS patients." (PMID 35457152, 2022). "Concentrations of ADPN, apelin, leptin, omentin, resistin, visfatin, and the L/A ratio were found to correlate with parameters of lipid metabolism in girls diagnosed with menstrual disorders and hyperandrogenism." (PMID 41303021, 2025). "CpG hypomethylation in genes such as AKR1C3, GHRHR, MAMLD1 and RETN, and hypermethylation in TNF, which can indirectly contribute to androgen excess, were consistent with increased and decreased levels of the respective gene transcripts." (PMID 30975191, 2019). "Recent research has shown that CpG hypomethylation regarding GHRHR, AKR1C3, RETN, and MAMLD1 and hypermethylation regarding TNF, which can indirectly contribute to androgen excess, were consistent with increased and decreased levels of the corresponding gene transcripts, respectively." (PMID 33763111, 2021).
hyperlipidemia (6 papers, 2017 to 2025). "The aim of our study was to investigate the influence of haemolysis and lipemia on resistin (RES) and myeloperoxidase (MPO) measurement by BioVendor enzyme-linked immunosorbent assays (ELISA)." (PMID 31015785, 2019).
kidney damage (6 papers, 2018 to 2025). "The data support that resistin is involved in the inflammatory process and favors arterial calcification Furthermore, it seems that there is a relationship between resistin and kidney damage in SLE cases." (PMID 36293458, 2022). "Within the context of nephropathy, adipokines, such as leptin, resistin, visfatin and chemerin, have their serum levels markedly correlated to the disorders observed in renal diseases." (PMID 30126255, 2018). "Elevated resistin levels may also contribute to the inflammatory burden seen in T1DM and increase the risk of complications such as cardiovascular disease and kidney damage." (PMID 40277935, 2025). "In the nutritional context, it has been shown that a low-energy diet applied in patients with nephropathy may decrease serum resistin levels and inflammation." (PMID 35684085, 2022).
leukemia (6 papers, 2014 to 2024). A malignant (clonal) hematologic disorder, involving hematopoietic stem cells and characterized by the presence of primitive or atypical myeloid or lymphoid cells in the bone marrow and the blood. "The serum RETN level in all patients was elevated and may serve as a potential clinical diagnostic marker to detect the recurrence of leukemia." (PMID 35111390, 2022). "Resistin (RETN), a proinflammatory cytokine, is elevated in a number of pathological disorders, including leukemia." (PMID 35111390, 2022). "Importantly, we found that heparanase potentiates the bioactivity of resistin in its standard bioassay in which monocytic human leukemia cell line, THP1, differentiates into adherent macrophage-like foam cells." (PMID 24465803, 2014). "Leukemia cells from most APL patients showed reduced PPARγ protein expression and enhanced resistin and TRIB3 protein levels compared with those in leukemia cells from non-APL patients." (PMID 32929351, 2020).
liver cirrhosis (6 papers, 2009 to 2023). "Further pointing to resistin levels reflecting liver function, serum resistin concentrations were induced in patients with liver cirrhosis or liver failure." (PMID 37238973, 2023). "In liver cirrhosis, resistin concentrations are comparable in the portal, hepatic and systemic blood." (PMID 28661458, 2017). "Systemic levels of adiponectin, omentin, resistin, galectin-3 and IL-6 are higher in patients with liver cirrhosis, while chemerin is reduced." (PMID 28661458, 2017). "In full agreement, an inverse relation of resistin levels and hepatic biosynthetic capacity in liver cirrhosis has been described." (PMID 19545363, 2009). "Macrophage activation is a common feature of liver cirrhosis, which may be reflected by a rise in serum resistin." (PMID 28661458, 2017).